HOXC13 (homeobox C13)
Diseases named in the same sentence as HOXC13 in open-access papers (continued):
Sharing a sentence is not in itself a finding about the gene and the disease.
lymphoid leukemia (1 paper, 2016). A malignant lymphocytic neoplasm of B-cell or T-cell lineage involving primarily the bone marrow and the peripheral blood. "Future experiments are required to determine the contribution of perturbations in Hoxc13 and Spi1 expression to dysregulation of Zfp521, and the potential for alternations in the expression of these transcription factors to promote lymphoid leukemia." (PMID 27506447, 2016). "However, based on the results of this study, the potential role of HOXC13 in lymphoid leukemia and B‐cell gene expression via regulation of Zfp521 should be explored." (PMID 27506447, 2016). "Yet to our knowledge there are no prior reports of HOXC13 involvement in lymphoid leukemia." (PMID 27506447, 2016).
non-small cell lung carcinoma (1 paper, 2023). A group of at least three distinct histological types of lung cancer, including non-small cell squamous cell carcinoma, adenocarcinoma, and large cell carcinoma. "In non-small cell lung cancer, silencing HOXC13 counteracts HOXC-AS2 overexpression-induced increases in cell proliferation and migration and decreases in cell apoptosis." (PMID 38057852, 2023).
oral cancer (1 paper, 2020). "HOXC13 was identified as the novel oral cancer driving genes." (PMID 32931492, 2020).
psoriasis (1 paper, 2022). An autoimmune condition characterized by red, well-delineated plaques with silvery scales that are usually on the extensor surfaces and scalp. "All selected hub genes present a similar expression pattern among AA, psoriasis, and AGA data sets, except four genes, including CHAC1, COMP, and HOXC13." (PMID 35983595, 2022).
triple-negative breast carcinoma (1 paper, 2025). An invasive breast carcinoma which is negative for expression of estrogen receptor (ER), progesterone receptor (PR), and human epidermal growth factor receptor 2 (HER2). "Interestingly, miR-26a-5p was found to negatively regulate HOXC13, a transcription factor whose expression was highest in triple-negative breast cancer and associated with poor immunotherapy response." (PMID 40861477, 2025).
cancer (20 papers, 2013 to 2025). A tumor composed of atypical neoplastic, often pleomorphic cells that invade other tissues. "In addition, the association of HOXC13 with other cancers has been confirmed." (PMID 38057852, 2023). "HOXC13 and GATA2 have been linked to a poor prognosis and aggressive phenotypes in a number of cancer lineages." (PMID 40858590, 2025). "The pan-cancer analysis further demonstrated that HOXC13 is upregulated in multiple tumor types, and its expression correlates with increased tumor cell proportions and decreased CD8+ T cell infiltration." (PMID 40861477, 2025). "The results showed that HOXC13 had a high expression in HER2 cancers and E2F8 had a high expression in basal-like cancers compared with normal tissues." (PMID 36814821, 2023). "Cyclin E has been implicated in various carcinomas; specifically, CCNE1 (Cyclin E1) is upregulated by HOXC13 to promote proliferation and cell cycle progression." (PMID 34692847, 2021). "Preliminary data, carried out on a multitumor tissue array to investigate HOXC13 distribution on several types of human cancer (unpublished data), showed the aberrant expression of HOXC13 protein in a small series of LPSs." (PMID 24085196, 2013). "HOXA1, HOXD10 and HOXC13 are strongly correlated with cancer hallmarks." (PMID 40676709, 2025). "Studies have supported the oncogenic role of HOXC13 in different cancers." (PMID 37407582, 2023). "HOXC13 promoted the growth of cancer cells and inhibited their apoptosis." (PMID 35456485, 2022). "Furthermore, pan-cancer analysis showed HOXC13 was highly expressed in 17 types of cancer." (PMID 40861477, 2025). "HOXA1, HOXC13 and HOXD10 were significantly correlated with the cancer hallmarks driving oral carcinogenesis." (PMID 40676709, 2025). "PITX2, HOXC13, and BARX1 act as transcription factors, and have been widely investigated in cancers." (PMID 26771237, 2016). "Notably, HOXA1, HOXC13 and HOXD10 were strongly correlated with cancer hallmarks, indicating their regulatory role in carcinogenesis." (PMID 40676709, 2025). "Although the entire HOX network plays a central role in cancer development and progression, the most posterior genes of the network, HOX13 paralogues (HOXA13, HOXB13, HOXC13 and HOXD13), specifically, are crucial in modulating these processes, in cooperation with co-localizing lncRNAs." (PMID 31137568, 2019). "Five of the genes affected by a single technology indel (WGS) in the MSI tumor (GNAS, HOXC13, MAPK1, and ZFHX3) and two of the genes affected by a single technology indel (WGS) in the MSS tumor (GNAS and HOXD13) were also listed in the cancer gene census list of the COSMIC database." (PMID 28683819, 2017). "Preliminary results, obtained by immunohistochemistry on a Multi-Tumor Array, in which a large spectrum of human cancer types was included, showed an increased HOXC13 expression particularly in LPS samples (data not shown)." (PMID 24085196, 2013).
tumor (12 papers, 2009 to 2025). "The miR-26a-5p/HOXC13 axis represents a newly identified pathway with significant implications for immunotherapy response and tumor progression." (PMID 40861477, 2025). "Spatial transcription analysis showed HOXC13 was positively correlated with tumor cell proportions (r = 0.68, p < 0.01) and negatively with CD8+ T cell infiltration (r = -0.54, p < 0.01)." (PMID 40861477, 2025). "IHC staining showed that HOXC13 was highly expressed in tumor tissues compared to paracancerous tissues and was also highly expressed in tumor tissues with high GS." (PMID 38057852, 2023). "The performed statistical analysis reveals for both HOXA13, HOXC13, HOXD13 a strong association with tumor grading classification." (PMID 34208964, 2021). "For the posterior HOXC genes we observed a significant reactivation of HOXC11 and HOXC13 in tumor tissues (HOXC13 p = 0.001)." (PMID 25994132, 2015). "In addition, HOXC13 was highly expressed in tumor tissues and correlated with Gleason score and pathological grade." (PMID 38057852, 2023). "Knocking down Bmi-1 induces cell-cycle arrest and rescues the mRNA levels of tumor-suppressive p16INK4ahomeobox A9 (HOXA9) and homeobox C13 (HOXC13) genes." (PMID 22967049, 2012). "Notably, several basal progenitor state factors (Hoxc13, Pax9, Gli2, Krt15) displayed paradoxical downregulation, indicating that EY-driven transcriptional changes do not reflect a physiologic OEPC cell state, but rather constitute a unique cellular state related to tumor initiation." (PMID 37961717, 2023). "Our data showed the absence of expression of HOXA13, HOXB13, HOXC13 and HOXD13 in the normal mucosa, a slight increase in expression in the transitional mucosa, up to in many cases over-expressed in the tumor." (PMID 30541551, 2018).
adenocarcinoma (1 paper, 2016). A common cancer characterized by the presence of malignant glandular cells. "Therefore, BMI‐1 induced HOXC13 repression may cause abnormal cell proliferation contributing to adenocarcinoma." (PMID 27506447, 2016).
HOXC13 also shares sentences with these, for which no sentence is quoted: liposarcoma (2 papers); mediastinal tumours (2); Alopecia universalis (1); Carvajal syndrome (1); dysplasia (1); esophageal cancer (1); esophageal squamous cell carcinoma (1); esophageal tumors (1); gastric cancer (1); hemangioblastoma (1); hypotrichosis 4 (1); hypotrichosis 6 (1); ichthyosis (1); myeloid leukemia (1); Nail dystrophy (1); Netherton syndrome (1); odonto-onycho-dermal dysplasia and (1); odontogenic tumors (1); oral diseases (1); oral squamous cell carcinoma (1); osteosarcoma (1); phyllodes tumor (1); scalp-ear-nipple syndrome (1); Schöpf-Schulz-Passarge syndrome (1); squamous cell carcinoma (1); type 2 diabetes (1).